IL1B (interleukin 1 beta)
Diseases named in the same sentence as IL1B in open-access papers (continued):
Sharing a sentence is not in itself a finding about the gene and the disease.
colitis (continued). "The pretreatment with A. muciniphila alleviated the phenotype of DSS-induced colitis mice through activating NLRP3 and decreasing the expression of pro-inflammatory cytokines (IL1β, IL-6) and chemokines MCP-1." (PMID 41488633, 2025). "In DSS-induced colitis, UA lowered IL-6 levels and attenuated inflammatory cell infiltration, while in LPS-induced lung injury, it suppressed TNF-α, IL-1β, and IL-6 production while upregulating anti-inflammatory IL-10 expression." (PMID 40804950, 2025). "In UC mucosa, there is induction of anti-commensal IgG, and commensal-IgG immune complexes target FcγR-expressing macrophages, thereby stimulating ROS-dependent production of IL-1β, type 17 immunity, and eventually exacerbating DSS-colitis." (PMID 41194916, 2025). "A study on TNBS-colitis (equivalent to CD) as a model of Th1 disease showed increased production of TNF-α, IL-1β, and IFN-γ in colonic submucosal macrophages, and OCT treatment reduced all these effects." (PMID 40508145, 2025). "A significant increase in the production of pro-inflammatory cytokines (e.g., IL-1β, TNF-α, and IL-6) by macrophages was observed in the dextran sodium sulfate (DSS) colitis mouse model." (PMID 40508145, 2025). "In animal models, wedelolactone alleviated DSS-induced colitis by blocking NF-κB and MAPK pathways, suppressing NLRP3 inflammasome activation, and promoting AMPK signaling, thereby reducing IL-1β release and tissue injury." (PMID 41304898, 2025). "NLRP3 mediates the conversion of pro-caspase-1 to its mature form to generate IL-1β and IL-18, while caspase-1-mediated inflammasome pathways control TNBS-induced colitis in mice." (PMID 40244120, 2025). "Further ELISA and qRT-PCR results showed that the protein and mRNA levels of inflammatory factors IL1-β, IL6, G-CSF and CXCL1 in the colon tissue homogenates of KO colitis mice were significantly higher than those of WT mice." (PMID 41417165, 2025). "The upregulation of pyyb and y8b observed in infected tilapia resembled findings in rodent colitis models, where NPY expression was induced by pro-inflammatory mediators such as TNF-α and IL-1β." (PMID 41007974, 2025). "As an emerging next-generation probiotic, PG can reduce the levels of pro-inflammatory cytokines IL-1β and TNF-α in mice with colitis, alleviate inflammatory damage, and maintain the integrity of the intestinal epithelium." (PMID 40400666, 2025). "Our observations indicated that muscone downregulated the expression levels of proinflammatory cytokines, including IL-1β, IL-6, TNF-α, IL-17, and IL-33, in DSS-induced colitis." (PMID 40452925, 2025). "In DSS-induced colitis mice, CGA alleviates symptoms and reduces inflammatory markers like colonic macrophage inflammatory protein 2 and IL-1β mRNA expression, suggesting its potential to regulate immune responses in intestinal inflammation." (PMID 40225345, 2025). "In the DSS-induced colitis model of mice, after PKM2 succinylation, PKM2 translocated into the nucleus, formed a transcription complex with HIF1a, and directly bound to the IL-1b promoter gene and commenced its transcription." (PMID 40865948, 2025). "In a severe colitis rat model, AMSC transplantation improved colitis by inhibiting monocyte/macrophage activity, lowering inflammatory markers (TNF-α, IL-6, and IL-1β), and preventing NF-κB activation." (PMID 40076934, 2025). "The Nlrp3 inflammasome mediates intestinal inflammation in UC by sensing stress, promoting the secretion of IL-1β and IL-18, epithelial damage, and immune activation, and is upregulated in DSS-induced colitis." (PMID 40995471, 2025). "In a DSS-induced colitis mouse study, puerarin markedly reduced colon inflammation by inhibiting the NF-κB pathway—treated mice had significantly lower myeloperoxidase activity and reduced levels of TNF-α, IL-1β, and IL-6 in colonic tissue." (PMID 41008518, 2025).
colitis (continued). "paracasei L9 expressing Amuc_1100 protein, mRNA levels of pro-inflammatory cytokines (IL-6, TNF-α, and IL-1β) and anti-inflammatory cytokines (IL-4 and IL-10) were measured in colon tissues of DSS-induced colitis mice." (PMID 41515240, 2025). "In acetic acid-induced colitis models, G. fisheri reduced TNF-α and IL-1β levels while modulating tight junction proteins." (PMID 40077614, 2025). "Limonin reduced the generation of proinflammatory cytokines TNF-α, IL-1β, and IL-6 as well as the expression of inflammatory proteins COX-2 and iNOS in the colonic tissues of mice with DSS-induced colitis." (PMID 40078988, 2025). "Our previous study demonstrated a significant elevation of IL-6, TNF-α, IL-1β, IL-17, IFN-γ and MCP-1 in colitis and showed that activation of the CB2 receptor by HU308 significantly reduces these cytokine levels." (PMID 40005963, 2025). "Another study also found that Galectin-3 expression contributes to acute DSS-induced colitis by activating the NLRP3 inflammasome and producing IL-1β in macrophages." (PMID 40534879, 2025). "In a murine model of acetic acid-induced colitis, pregabalin reduced both macroscopic and microscopic intestinal damage and inflammation, decreasing colonic levels of TNF-α, IL-6, IL-1β, and myeloperoxidase (MPO) activity [DOI: 10.4103/1735-5362.329924]." (PMID 40650291, 2025). "Macrophage TIM3 can inhibit the expression of proinflammatory cytokines such as TNFα, IL-1β, IL-6, IL-12, and NOS2 in dextran sodium sulfate (DSS)-induced colitis." (PMID 41307843, 2025). "In parallel with these findings, garlic-derived exosome-like nanovesicles suppressed IL-6, IL-1β, TNF-α, and IFN-γ levels, TLR4 and Myd88 pathways in LPS-treated Caco2 cells, and the dextran sulfate-treated mouse colitis model." (PMID 40149930, 2025). "In the current study, AVCP administration significantly reduced the elevated serum levels of IL-1β, IL-6, TNF-α, and IL-17A induced by DSS in mice, which suggests that AVCP can reduce inflammation in colitis mice." (PMID 40507195, 2025). "Mechanistically, L. curvatus DCF0620 treatment controlled the infiltration of cells that express pro-inflammatory cytokines (TNF-α, IL-1β, IL-6, and IL-17) and fibrotic markers (TGF-β, Col1, and α-SMA) into the intestinal tissue of DSS-induced colitis mice." (PMID 41567191, 2025). "We also showed that culturing UC lamina propria mononuclear cells (LPMCs) with NETs resulted in enhanced production of TNF-α and IL-1β, and inhibition of NET release attenuated DSS-colitis in mice." (PMID 41194916, 2025). "The elevated levels of IL-1β, IL-23 and TNF-α in colon tissues are often used as a biomarker of the severity of colitis." (PMID 40943092, 2025). "IL-1β, a pro-inflammatory cytokine secreted primarily by macrophages, was also found to be overexpressed in DSS-colitis mice." (PMID 40497975, 2025). "In response to DSS-induced colitis, pro-inflammatory cytokine levels (TNF-α, IL-1β, IL-6, IFN-γ, NF-κB, IL-17, and TGF-β) were significantly elevated in group 2, indicating their role in the pathogenesis of UC." (PMID 40502390, 2025). "It is well known that pro-inflammatory factors such as TNF-α, IL-1β, IL-6, and IFN-γ play important roles in colitis progression." (PMID 40529132, 2025). "Previous studies have reported that excessive secretion of IL-1β in IBD patients and mouse colitis models." (PMID 39899477, 2025). "In a DSS‐colitis recovery model, WMP promoted recovery as evidenced by improved weight gain, reduced stool scores, reduced IL‐1β levels, and myeloperoxidase (MPO) activity in colonic tissue." (PMID 40509652, 2025). "In mouse models of DSS-induced colitis, deletion of IRAK3 significantly lowers serum IL-1β levels and reduces intestinal inflammation." (PMID 40979590, 2025). "TTM significantly reduced colonic inflammation and the levels of IL-6, IL-1β, and TNF-α in colitis mice." (PMID 40969742, 2025).
colitis (continued). "The study found that CW notably reduced the mRNA levels of pro‐inflammatory markers including TNF‐α, IL‐1β, IL‐6, Toll‐like receptor 4 (TLR4), and iNOS, while it enhanced the expression of the anti‐inflammatory cytokine IL‐10 in colitis." (PMID 39830908, 2025). "It has been demonstrated in a model of TNBS-induced colitis that a rise in SOD activity inhibits the production of proinflammatory cytokines TNFα and IL-1β, which are enhancers of ROS production due to the promotion of endosomal internalization of Nox1." (PMID 40305159, 2025). "In our study, SC significantly reduced TNF-α, IL-1β, IL-8, and IL-18 levels in UC mice, reinforcing its anti-inflammatory potential against DSS-induced colitis." (PMID 39936162, 2025). "Specifically, the abundance of Bacteroides and Escherichia-Shigella as opportunistic pathogens was significantly positively correlated with key pathological markers of colitis such as MPO, MDA, TNF-α, IL-6, and IL-1β." (PMID 41010513, 2025). "Colonic tissues from DSS‐induced colitis models exhibited significantly increased TNF‐α, IL‐1β, and IL‐18 levels relative to healthy controls (p < 0.01)." (PMID 40994452, 2025). "The current study certificates that quercitrin alleviates the colitis model by enhancing tumor necrosis factor α (TNF-α) and interleukin 1β (IL-1β) expressions." (PMID 38397537, 2024). "In DSS-induced colitis, pre-treatment with DHA-PL and DHA-enriched triglyceride (DHA-TG) for 14 days downregulated pro-inflammatory IL-1β and TNF-α and upregulated anti-inflammatory IL-10 protein expressions." (PMID 38672464, 2024). "In our experimental study, we observed a significant increase in the mRNA expression levels of pro-inflammatory cytokines, including IL-1β, IL-6, and TNF-α, following DSS administration, indicative of colitis induction in mice." (PMID 38760355, 2024). "In studies of colitis, it has been found that the abundance of Alistipes is negatively correlated with TNF-α and IL-1β levels." (PMID 39410114, 2024). "In mice with DSS-induced colitis, VI-16 intervened by inhibiting NLRP3 inflammasome-related IL-1β release and reducing oxidative stress." (PMID 39684769, 2024). "Various colitis symptoms in mice, including body weight, thymus index, spleen index, IL-6, TNF-α, IL-1β, IL-10, and IgA, were restored with 100 mg/kg PSPRS and 300 mg/kg PSPRS administration." (PMID 38611336, 2024). "Decrease the severity of DSS-induced colitis and the production of pro-inflammatory cytokines such as tumor necrosis factor (TNF)-α, IL-6, and IL-1β." (PMID 39767818, 2024). "HFD feeding resulted in colitis: it elevated myeloperoxidase, TNF-α, IL-1β, and IL-6 levels, NF-κB activation (p-p65/p65), and NF-κB+CD11c+ cell number and decreased IL-10 and SIRT1 levels and AMPK activation (p-AMPK/AMPK) in the colon." (PMID 39599597, 2024). "Inflammatory factors such IFN-γ, TNF-α, and IL-1β can induce the expression of GBP5; these cytokines are highly expressed in IBD and in the experimental mouse models of colitis." (PMID 39062588, 2024). "These cytokines play critical roles in the pathogenesis of colitis, with IL-6, TNF-α, and IL-1β promoting immune cell recruitment and tissue damage, while MCP-1 contributes to macrophage activation and mucosal injury." (PMID 39682761, 2024). "In trinitrobenzenesulfonic acid (TNBS)-induced colitis in rats, inosine was shown to reduce macroscopic injury, as well as levels of MDA, MPO, IL-1β and TNF-α in colonic tissue, in part, through the activation of A2AAR." (PMID 38474346, 2024). "The results demonstrated that SP decreased mRNA levels of IL-6, TNF-α, IL-17A, and IL-1β, but enhanced the mRNA level of IL-10 in mice with DSS-induced colitis." (PMID 38725846, 2024). "The reduction in expression level of NLRP3 and its activity was further validated by measuring IL-1β, IL-13, MPO, and NO in colitis-induced mouse model." (PMID 37902927, 2024).
colitis (continued). "The mRNA expression of proinflammatory cytokines in colonic tissues, including IL-1β, IFN-γ, and TNF-α, were decreased in DSS-induced colitis mice treated with NI1 and TJ5 as compared to mice solely treated with TJ5." (PMID 38946731, 2024). "Apigenin treatment inhibited colon damage, MPO activity, and the production of IL-1β, TNF-α, and IL-6 in DSS-induced colitis, as well as the NF-κB and STAT3 pathways in colitis-associated colon cancer tissues in mice." (PMID 39451206, 2024). "Studies indicate that Gal-3 induces NLRP3 (NLR family pyrin domain-containing 3) inflammasome activation in macrophages in a model of dextran sulfate sodium (DSS)-induced colitis, while macrophages of Gal-3 knock-out mice produce less TNF-α and IL-1β." (PMID 39125698, 2024). "Quercetin can alleviate inflammation by reducing the levels of TNF-α, IL-1β, IL-6, and IL-10, thus treating DSS-induced colitis in mice." (PMID 38902425, 2024). "An intriguing finding of our study is the discovery of IL-1β and caspase-1 activation by DSS-induced colitis, which accounts for pyroptosis." (PMID 38491049, 2024). "In an in vivo study, Kumujan B inhibited the expression of IL-1β, IL-6, and TNF-α and improved the colon barrier function in dextran sulfate sodium salt (DSS)-induced experimental mice colitis." (PMID 39148547, 2024). "L-theanine suppressed the expression levels of TNF-α, IL-1β, IL-6, iNOS, and COX-2 in DSS-induced colitis, and relieved phosphorylation of GSK-3β and Akt/mTOR in Cd-induced ICR mice." (PMID 39572022, 2024). "At the level of mRNA, the relative expression of TNFα, IL1β, IL6, MMP9, and PTGS2 increased significantly in DSS-induced colitis compared with the control group." (PMID 39064786, 2024). "They tested this concept using ELISA and discovered that IL-1β, IL-6, and TNF-α were significantly induced in the colon tissue of DSS-induced colitis mice, indicating a potent anti-inflammatory mechanism." (PMID 39323474, 2024). "Our data revealed a significant upregulation of IL-1β, IL-2, and TNF-α levels in the colitis mice model." (PMID 38613088, 2024). "In addition, one study also found that fermented wild ginseng could relieve the symptoms of colitis in a DSS-induced colitis animal model through inhabiting secretion level of proinflammatory cytokines (IL-1β, IL-6, IL-12, p40, TNF-α, and IFN-γ) and blocking NF-κB signaling pathway." (PMID 38698858, 2024). "Results revealed an upregulation of IL-10 expression and a downregulation of IL-1β and IL-6 expression in T. spiralis- infected mice compared to DSS- treated mice alone during the induction of colitis." (PMID 39495798, 2024). "Administration of nanoparticle with overexpressed miR-223 showed amelioration of experimental colitis, and decrease of NLRP3 levels and IL-1β secretion." (PMID 38323035, 2024). "In a mouse model of TNBS colitis, intervention with the CXCR2 inhibitor SB225002 significantly reduced tissue damage, inflammation and levels of IL‐1β, MIP‐2, iNOS and KC, thereby improving survival." (PMID 39199011, 2024). "Inflammatory cytokines and mediators such as IL-1β, IL-6, and TNF-α are pivotal in initiating and sustaining colitis." (PMID 39061864, 2024). "A key feature of AA-induced colitis is immune cell infiltration, producing high levels of proinflammatory cytokines such as TNF-α and IL-1β." (PMID 39199130, 2024). "For example, a previous study reported that ZnO nanoparticles reduced the elevated concentrations of IL-1β and TNF-α in a model of DSS-induced colitis." (PMID 38998031, 2024). "In another acetic acid-induced colitis rat model, ghrelin markedly improved colonic blood perfusion, enhanced superoxide dismutase (SOD) activity, and lowered the concentrations of IL-1β and MDA, thus exerting a protective role." (PMID 38275675, 2024).
colitis (continued). "The results showed that ZSS polysaccharide (20 mg/kg) significantly improved the severity of colitis in colitis rats and inhibited the inflammatory response by reducing the activity of TNF-α, IL-1β, IL-6 and MPO in colitis rats." (PMID 39679366, 2024). "Mononuclear phagocytes and epithelial cells in the intestine can drive inflammatory cytokines, including IL-1β, TNF-a, and IL-6, which are involved in the occurrence and progression of colitis." (PMID 39458282, 2024). "Consistent with the high LPS load in serum, the expression level of inflammatory cytokines TNF-α, IL-1β, and IL-6 significantly increased in the colons of mice with DSS-induced colitis." (PMID 39272608, 2024). "As previously reported, Zanthoxylum peel extract can inhibit the expression of TNF-α, IL-1β, and IL-12 by regulating TLR4 and TLR4-related pathways in experimental colitis induced by DSS in mice and LPS-induced inflammation in J774.1 cells." (PMID 39519671, 2024). "Gal-3 is known to play a pivotal pro-inflammatory role during the induction phase of acute colitis, facilitating NLRP3 inflammasome activation and subsequent IL-1β production." (PMID 38172822, 2024). "The latest research shows that secoisolariciresinol diglucoside alleviates colitis by inhibiting NLRP1 inflammasomes, correlating with reduced IL-1β, IL-18, and TNF-α levels in DSS-induced colitis mice." (PMID 38455052, 2024). "IFX and 1,25-dihydroxyvitamin D3 (VitD3) synergistically prevented the development of colitis by improving clinical signs, pathological and hematological manifestation, and inhibiting intestinal inflammation (decreasing TNF-α, IL-1β, and IL-6)." (PMID 39055880, 2024). "We estimated the effect of XYKJP on inflammatory cytokines in colitis tissues and found that XYKJP treatment led to a reduction in the levels of IL-1β, TNF-α, and IL-6, and a significant improvement in the level of IL-10 and IL-22, as demonstrated by ELISA." (PMID 39133435, 2024). "Meanwhile, Bacteroides vulgatus can also reduce the expression of colon TNF-α, IL-1β and IL-6 induced by DSS and improve colitis in mice." (PMID 39003416, 2024). "Red cabbage alleviated colitis and intestinal inflammation by decreasing IL6, IL1β, TNFɑ, iNOS, and COX-2 concentrations in DSS mice." (PMID 38779039, 2024). "NLRP3 inflammasome activation and IL-1β release is a major pathology in the UC patients and also in the DSS-induced colitis model." (PMID 38417794, 2024). "An increased Nrf2 expression in the colorectal mucosa of mice along with a decreased expression of TNF-α, IL-1β, IL-6, IFN γ, NF-κB, COX2, and iNOS were also found after a 4 week supplementation with crocin in DSS-induced colitis." (PMID 38543230, 2024). "More importantly, combined SFELNVs and CX5461 alleviated mice colitis by inhibiting pro-inflammatory factors (TNF-α, IL-1β, and IL-6) expression and promoting M2 macrophage polarization." (PMID 39379937, 2024). "Astaxanthin significantly suppressed the mucosal mRNA expression of pro-inflammatory cytokines, including IL-1β, IL-6, TNF-α, IL-36α, IL-36γ, and COX-2, in DSS colitis." (PMID 38672464, 2024). "We observed significant increases in colonic IL-6, IL-1β, MCP-1, and TNF-α levels in colitis, which were effectively reduced by CBD and HU308 treatments." (PMID 39682761, 2024). "Studies have shown increased IL-1β levels in the intestines of IBD patients, and blocking IL-1β activity has been found to reduce inflammation and improve symptoms in experimental colitis models." (PMID 38891863, 2024). "We revealed that LA exerted proinflammatory effect on macrophages, which increased the expression of IL‐6, and IL‐1β and decreased the expression of TGF‐β, inhibited Treg cell differentiation, and increased susceptivity to DSS‐induced colitis." (PMID 38477534, 2024). "Further, IL-1β- and NLRP3-null mice have shown significantly reduced inflammatory response and colitis development." (PMID 39769450, 2024).